ERBB2 (erb-b2 receptor tyrosine kinase 2)
Diseases named in the same sentence as ERBB2 in open-access papers (continued):
Sharing a sentence is not in itself a finding about the gene and the disease.
colorectal cancer (continued). "The availability of NGS facilitates a therapeutic genomic paradigm to classify CRC based on actionable genomic biomarkers such as RET, ALK, NTRK, ROS and ERBB2, which may facilitate the clinical trial development of a Colorectal Cancer Genomic Protocol." (PMID 26078337, 2015). "While acquisition of novel mutations may be one of the possible explanations to this resistance in clinical treatment, activating mutations of several RTKs including ErbB2, ErbB3 and c-MET were discovered in human colorectal cancer and other cancers." (PMID 24205104, 2013). "In order to identify suitable human colorectal cancer cell lines corresponding to the three molecular patterns which we discovered in the human samples, the expression of ErbB2, ErbB3 and c-MET in 9 human colorectal cancer cell lines was analyzed by western blotting (data not shown)." (PMID 24205104, 2013). "Therefore, in the present study, we investigated the differential expression of RTKs c-MET, ErbB2, ErbB3, and down stream signaling molecules in primary samples of colorectal cancer patients, as well as in representative human colorectal cancer cell lines." (PMID 24205104, 2013). "For instance, the expression levels of both ErbB2 (HER2) and ErbB3 (HER3), the members of the RTK family, were found to be elevated in colorectal cancer (CRC) cells when exposed to Listeria monocytogenes supernatant." (PMID 39948481, 2025). "We also validated 7 of the genes recently identified as colorectal cancer driver genes, including two known drug targets, IDH1 and ERBB2." (PMID 41413856, 2025). "In cases of equivocal IHC score of 2+ in breast, gastric, and colorectal cancers, reflex in-situ hybridization (ISH) is performed to confirm ERBB2 amplification." (PMID 40098704, 2025). "For example, in the monitoring of advanced colorectal cancer, ctDNA enables the dynamic and repeated assessment of changes in multiple key molecules of the tumor, such as EGFR, ERBB2, PIK3CA, and MAP2K1, among others." (PMID 39184861, 2024). "In colorectal cancer, ESMO suggests that an optimal gene panel should detect KRAS, NRAS, BRAF, NTRK, and ERBB2 amplification, although NGS is still only considered for research purposes." (PMID 38213074, 2024). "Some top-ranked candidates were PIM1 in bladder cancer (FDR ≈ 1%), ZFHX4 in colorectal cancer (FDR ≈ 1%), ERBB2 in prostate, stomach, breast luminal subtype, and bladder cancers (FDR ranging from 4% to 14%) and others." (PMID 39033140, 2024). "The study data include two cohorts focusing on patients with colorectal cancer (CRC), one with ERBB2 amplifications and the other with either ERBB2 or ERBB3 (ERBB2/3) mutations, who received treatment with pertuzumab plus trastuzumab." (PMID 39682117, 2024). "EGFR and ERBB2 expression was mainly measured by immunohistochemistry methods in primary tumours and CRC metastases, whereas ERBB2 and MET expression was measured in colorectal cancer cells in the same population." (PMID 36890818, 2023). "The tumor group showed similar expression of the highly expressed oncogenes in colorectal cancer, including previously reported EGFR and ERBB2, and the solute carrier (SLC) family." (PMID 36459282, 2022). "lncRNA CASC9 expression was increased in primary colorectal cancer samples, and CASC9 initiates CRC development by regulating miR‐193a‐5p/ERBB2 axis." (PMID 32533587, 2020). "For example, high copy numbers of ERBB2, TOP2A, CCND1, EGFR and MYC are observed in many colorectal cancers." (PMID 31009485, 2019). "The copy number gain of ERBB2, RECQL4, and MYC oncogene and MAGEB family has been frequently reported in colorectal carcinoma, as shown in a recent review." (PMID 27481518, 2016). "Sera from colorectal cancer (n = 67) and colon benign tumor patients (n = 5) were analyzed for the presence of auto-antibodies to ribosomal P proteins (P0/P1/P2), CEA, EGFR and ErbB2." (PMID 25889931, 2015).
colorectal cancer (continued). "In colorectal carcinoma cells, blocking both PTGS2 (COX-2) and the ERBB2 (HER2) pathways synergistically reduced tumor growth." (PMID 24213116, 2011). "In colorectal carcinoma, EGFR (ErbB1) signaling remains a cornerstone of oncogenic drive, while the HER2 (ErbB2) and HER3 (ErbB3) axis has gained increasing recognition for its role in tumor progression, therapy resistance, and compensatory signaling when EGFR is inhibited." (PMID 41515404, 2025). "Another biomarker analysis from the DESTINY-CRC01, including patients with advanced colorectal cancer, showed that T-DXd efficacy is correlated to higher baseline HER2 levels in both tissue (IHC/ISH) and peripheral blood (copy number of ERBB2 in plasma and circulating HER2-extra cellular domain)." (PMID 39062065, 2024). "Genetic alterations in ERBB2 have been established as a biomarker for targeted anti-human epidermal growth factor receptor 2 (HER2) therapy in patients with multiple types of solid tumors, including gastrointestinal malignancies such as gastroesophageal, gastric, and colorectal cancers." (PMID 38103030, 2024). "Furthermore, we conducted FISH on 12 additional FFPE samples obtained from 11 colorectal cancer patients (seven males, four females), all previously identified as ecDNA+ for cargo genes MYC or ERBB2 by GCAP." (PMID 38373991, 2024). "CNVs were determined across a set of 10 lung, breast, and colorectal cancer samples harboring a total of 11 known CNVs in the EGFR, MET, and ERBB2 genes as determined by orthogonal methods, including the OPA, OFA, and INFORM HER2 FISH assays." (PMID 37762091, 2023). "Amplification of ERBB2, or the HER2 gene, is seen in up to 5% of KRAS wild type colorectal cancer." (PMID 35565354, 2022). "Due to the high incidence worldwide of colorectal cancer, anti-HER2 targeted therapies have recently become an attractive matter of investigation, even if the incidence of ERBB2 genomic alterations is relatively low among patients with metastatic colorectal cancer." (PMID 33946310, 2021). "Activation of ERBB2 signaling, e.g. through ERBB2 amplification, leads to persistent ERK 1/2 signaling, which was shown to be the principle mechanism of both primary and secondary resistance to cetuximab-based therapy in colorectal cancer patients." (PMID 24676216, 2014). "All the cases examined could be classified as: ErbB3: c-MET co-over-expression colorectal cancer, ErbB3:ErbB2 co-over-expression colorectal cancer, and ErbB3:ErbB2: c-MET co-over-expression colorectal cancer." (PMID 24205104, 2013). "Using ErbB2 specific inhibitor Lapatinib and c-Met specific inhibitor PHA-665752, we further demonstrated that this constitutive activation of RTK signaling is necessary for the survival of colorectal cancer cells." (PMID 24205104, 2013). "In order to investigate further the mechanism of downstream signaling of both molecular patterns in colorectal cancer, cell lysates were utilized to analyze the activation of AKT and MAPK signaling which are well-known downstream signaling pathways of ErbB2/ErbB3 and ErbB3/c-MET complexes." (PMID 24205104, 2013). "Less frequent mutations were seen in genes that are typically considered “druggable” but not seen previously in colorectal cancer including KIT, ERBB2 and ALK." (PMID 33632293, 2021). "Contrarily to ERBB2, KRAS is not a target of the mAbs used in colorectal cancer." (PMID 31169290, 2019).
non-small cell lung carcinoma (486 papers, 2002 to 2026). A group of at least three distinct histological types of lung cancer, including non-small cell squamous cell carcinoma, adenocarcinoma, and large cell carcinoma. "We explored that destabilization of ERBB2 in this non-small-cell lung cancer line does, indeed, control these implicated kinases and proteins." (PMID 37359373, 2023). "Mutations in exon 20 of the ERBB2 gene (HER2) occur in approximately 3% of patients with advanced non-small cell lung cancer." (PMID 37895255, 2023). "The FDA extended and granted accelerated approval for unresectable or metastatic non-small cell lung cancer (NSCLC) with activating HER2 (ERBB2) mutations after progressing on prior therapy on 11 August 2022." (PMID 37568702, 2023). "Non-small cell lung carcinoma (NSCLC) cases with next-generation sequencing proven ERBB2 point mutations (n=8) or amplifications (n=11) were assessed with commercially available ERBB2 (HER2) immunohistochemical antibodies." (PMID 37363568, 2023). "We transfected the four destabilized (des) clones (desARE3’UTR ERBB2-1, desARE3’UTR ERBB2-2, desARE3’UTR ERBB2-3, desARE3’UTR ERBB2-4) and desARE3’UTR ERBB2-30 into non-small-cell lung cancer cells that carry mutation in the EGFR T790M but expresses ERBB2." (PMID 37359373, 2023). "For example, research revealed that EGFR was amplified and/or mutated in glioma and non-small-cell lung cancer, whereas ErbB2 was amplified in breast, ovarian and bladder cancer and in several other tumors." (PMID 30984788, 2019). "Overexpression, amplification and occasionally activating mutations of ErbB2 also occur in other cancers, including non-small cell lung cancer." (PMID 25238247, 2014). "ErbB2 heterodimerises with EGFR and ErbB2 mutations have recently been reported within a subset of non-small cell lung cancer (NSCLC)." (PMID 17224925, 2007). "In addition, 4% of non-small cell lung carcinomas were shown to have ERBB2 mutations in the kinase domain." (PMID 17150109, 2006). "HER2 (ERBB2) mutations, particularly exon 20 insertions, are rare but actionable oncogenic drivers in non-small cell lung cancer (NSCLC)." (PMID 41426315, 2025). "We have demonstrated here that the recalcitrant ERBB2 signal driving the EGFR T790M non-small cell lung cancer can be degraded by the engineered destabilized 3'UTR of ERBB2." (PMID 38699639, 2024). "The same is true for EGFR T790M non-small-cell lung cancer that is osimertinib-resistant with 6% of patients bearing ERBB2 amplification." (PMID 37359373, 2023). "For example, some target genes of the common IC-lncRNA RP11-445H22 have been used as anticancer drugs targets, such as CTLA4 as a target of radotinib in cutaneous melanoma, EGFR and ERBB2 as targets of afatinib in metastatic non-small-cell-lung-cancer." (PMID 36463330, 2022). "To date, there is no targeted therapy approved and demonstrated to be effective for non-small cell lung cancer patients with EGFR sensitizing mutations, and ERBB2 amplification." (PMID 33663050, 2021). "Rarely, dominantly inherited non-small-cell lung cancer (NSCLC) has been reported due to somatic mutations in EGFR/ErbB1 and ERBB2." (PMID 34274969, 2021). "Of the classic non-small-cell lung cancer oncogenic driver mutations, only two were detected in two patients, a KRAS G12D in a stage IIIA patient (P27) and an ERBB2 gene amplification in a stage IVA patient (P06)." (PMID 31659278, 2020). "For example, the three genes KRAS, EGFR, and ERBB2(HER2), which are found in the non-small cell lung cancer (NSCLC) signaling network, are key biomarkers." (PMID 29912931, 2018). "Here, we report our experience using next generation sequencing (NGS) to examine AKT1, BRAF, EGFR, ERBB2, KRAS, NRAS, and PIK3CA genes in 1006 non-small cell lung cancers in a clinical diagnostic setting." (PMID 29228562, 2017).
non-small cell lung carcinoma (continued). "EGFR has been found to be amplified in gliomas and non-small-cell lung carcinoma while ErbB2 amplifications are seen in breast, ovarian, bladder, non-small-cell lung carcinoma, as well as several other tumor types." (PMID 26635612, 2015). "More recently, EGFR and ErbB2 were reported as direct new substrates for this phosphatase in a non-small cell lung cancer cell line NSCLC." (PMID 24886454, 2014). "We set out to define novel ways to overcome resistance to lapatinib and understand downstream pathways of oncogenic ErbB2 signaling in ErbB2-dependent breast and non-small cell lung cancer cells." (PMID 25238247, 2014). "Eighteen patients suffering from ErbB2-expressing metastatic breast cancers, prostate cancers, head and neck cancer, non small cell lung cancer, or transitional cell carcinoma were treated." (PMID 16168106, 2005). "Non-small cell lung carcinomas do not commonly harbour ERBB2 mutations, with clinical trials conducted to assess for targeted response and progression-free survival." (PMID 37363568, 2023). "At present, no commercially available ERBB2 clone can accurately detect ERBB2 mutations consistently in non-small cell lung carcinoma specimens, but amplifications can be detected with reasonable diagnostic accuracy." (PMID 37363568, 2023). "It is approved in Non-small cell lung cancer (NSCLC) (55% objective response among 91 patients) based on the DESTINY-Lung01 for patients with ERBB2 kinase domain mutations and in metastatic breast cancer for patients with HER2 low expression by IHC." (PMID 37404765, 2023). "The ERBB2 F616L mutation that was detected in two patients’ samples is not considered a ‘classic’ activating mutation in non-small cell lung cancer." (PMID 34943612, 2021). "We observed that, similarly to its effect in SK-BR-3, the dual inhibition of EGFR and ErbB2 by lapatinib was able to decrease SOCE amplitude in non-small cell lung carcinoma cells (i.e. A549), epidermoid carcinoma cells (i.e. A431) and also in an embryonic cell line (i.e. NIH-3T3)." (PMID 29662626, 2018). "For example, the National Comprehensive Cancer Network (NCCN) guidelines for non-small cell lung cancer (NSCLC) recommend measurement of genomic alterations in seven different genes (EGFR, ALK, ERBB2 (encodes HER2 protein), BRAF, MET, ROS1 and RET) to guide twelve different matched therapies." (PMID 26474073, 2015). "The receptor tyrosine kinase ErbB2 (Her2/Neu) is overexpressed in 20% of breast cancers; epidermal growth factor receptor (EGFR) is highly expressed in non-small-cell lung cancers; and the FLT3 receptor is mutated in 30% of acute myelogenous leukemias (AML) and other hematological malignancies." (PMID 21049054, 2010). "More recently, a number of studies reported the presence of ERBB2 mutations located in the kinase domain (exons 19 and 20) in non-small cell lung carcinomas (NSCLC) that could potentially result in the activation of the tyrosine kinase activity of the receptor protein." (PMID 17150109, 2006). "For example, the systemic treatment of advanced non-small cell lung cancer remained conventional chemotherapy for several decades until the emergence of TKI therapy following the discovery of several driver mutations including EGFR, ALK, ROS1, MET, RET, BRAF, and ERBB2/HER2." (PMID 39409947, 2024). "For non-small cell lung cancer (NSCLC) the current clinical guidelines recommend testing for genomic alterations in EGFR, BRAF, ROS1, ALK, KRAS, NTRKs, MET, RET, and ERBB2 genes." (PMID 38398180, 2024). "The human epidermal growth factor receptor 2 (HER2, ERBB2) has been identified as an oncogenic driver in non-small cell lung cancer (NSCLC), with approximately 3% of patients with NSCLC harboring heterogeneous HER2 aberrations." (PMID 39012378, 2024). "Clinically relevant CNVs include ERBB2 amplification in breast cancer and EGFR and MET amplifications as a resistant mechanism in non-small cell lung carcinoma (NSCLC)." (PMID 35626061, 2022).
non-small cell lung carcinoma (continued). "The National Comprehensive Cancer Network (NCCN) guidelines recommend “broad molecular profiling”, including BRAF, ERBB2 (HER2), MET, RET, NTRK, and ROS1, in addition to EGFR and ALK for metastatic non-small cell lung cancer (NSCLC)." (PMID 32375398, 2020). "It was found that miR-331-3p could inhibit tumour cell invasion and metastasis by regulating ErbB2 and VAV2 to attenuate the epithelial–mesenchymal transition in non-small cell lung cancer." (PMID 38062510, 2023). "For example, when Itchy E3 ubiquitin protein ligase (ITCH) was increased in non-small cell lung cancer (NSCLC) cells by has_circ_0043256, it was observed to induce apoptosis, while an increase of ERBB2 in the nucleus pulposus (NP) cell by circGRB10 was reported to inhibit apoptosis." (PMID 34853728, 2021). "Never-smoker non-small cell lung cancer (NSCLC) represents a distinct molecular subtype enriched for actionable driver mutations, including ERBB2 (HER2) exon 20 insertions, which occur in approximately 2-4% of cases and are more common in women and individuals of Asian ancestry." (PMID 42058342, 2026). "Notably, these ERBB2 oncogenes were not translated to HER2 protein overexpression, reminiscent of ERBB2-mutant metastatic non-small cell lung cancer, where the oncogenicity of ERBB2 mutations do not require HER2 overexpression." (PMID 40726246, 2025).